AMACR (alpha-methylacyl-CoA racemase)
Diseases named in the same sentence as AMACR in open-access papers (continued):
Sharing a sentence is not in itself a finding about the gene and the disease.
tumor (122 papers, 2008 to 2025). "The integration of immunohistochemical (IHC) profiling, highlighting markers such as CK7, CD117, and AMACR, not only strengthened the diagnostic accuracy of subtypes but also facilitated the correlation between tumor biology and clinical behavior." (PMID 40895976, 2025). "In PCa, AMACR can cause DNA damage that leads to the expression of peroxide, which promotes tumor progression." (PMID 35795046, 2022). "The combination of SNPs with thehistopathological tumor data between allele variants of AMACR,AKT1+AR, and AKT1+AMACR indicated an associationwith protection against seminal vesicle invasion." (PMID 32484847, 2020). "After 2–3 months, we observed, from both WIT‐cultured primary basal/stem cells and luminal progenitors, the development of tumor‐like structures that stained positive for pAKT and AMACR, indicating the loss of PTEN in cancerous tissues." (PMID 28297567, 2017). "In GISTs, both AMACR amplification and AMACR overexpression were associated with larger tumor size, higher mitotic count, and higher risk levels defined by the NIH grading scheme." (PMID 25473890, 2014). "As seen in Table-1, those GISTs harboring amplified AMACR genes and overexpressed AMACR protein were strongly associated with the presence of epithelioid cells, large tumor size, higher mitotic rate (Figure-2B), and higher NIH risk levels (all p≤0.003)." (PMID 25473890, 2014). "Forty-one fresh tumor samples of various risk categories were enriched for pure tumor cells by laser capture microdissection and quantified for AMACR mRNA expression." (PMID 25473890, 2014). "In detail, AMACR elevation was significantly associated with higher tumour differentiation grade (G1 and G2) and advanced tumour stage." (PMID 24152881, 2013). "Although some studies have revealed that AMACR expression may be a marker of tumor differentiation in several cancer types, the mechanism underlying AMACR-mediated tumor differentiation is still elusive." (PMID 33755595, 2021). "Increased AMACR expression and its association with tumor venous invasion suggest that AMACR may play a role in HCC development and progression." (PMID 18577240, 2008). "Next, the correlations between AMACR expression and clinicopathological parameters such as age, sex, and tumor size were evaluated." (PMID 39336516, 2024). "Immunohistochemistry revealed diffusely positive expression of TFE3 and alpha-methylacyl-CoA-racemase (AMACR) in almost all tumor cells." (PMID 39206137, 2024). "In low-grade dysplasia, AMACR expression was significantly correlated with younger patients and smaller tumor size (p = 0.041 and 0.025, respectively)." (PMID 39336516, 2024). "Small areas of AMACR positively stained cells were observed within and outside the tumor regions identified by H&E supported pathology." (PMID 37719014, 2023). "In PCa, TET1 was frequently detected in alpha-methylacyl-CoA racemase (AMACR)–positive tumor cell clusters and was detectable at all tumor stages and Gleason scores." (PMID 34844636, 2021). "IF analysis with an AMACR antibody in tumor tissue showed an increase in AMACR levels compared to normal tissues." (PMID 33154941, 2020). "CELF5 was low-expressed in tumor cell line; AMACR, CYP27A1, CYP46A1, and CH25H were high-expressed in tumor cell line in CCLE." (PMID 32117422, 2019). "As expected, we found an up-regulation of AMACR expression in the tumor compared to the healthy gland whereas the expression of SIRT7 mRNA did not vary." (PMID 29100388, 2017). "The results of a recent paper indicated that strong AMACR expression has a slightly higher positive predictive value than does LGD for advanced neoplasia in the general BE population." (PMID 26486567, 2016).
tumor (continued). "When pyknotic cells were positive for cytokeratin, PSA, or AMACR on immunohistochemical staining, they were considered to demonstrate the presence of a viable residual tumor." (PMID 26269129, 2015). "We can conclude that AMACR mRNA expression level-based separation of epithelial cells generates cell populations that closely resemble tumor and benign prostate cells, with respect to their gene expression profile." (PMID 25514598, 2015). "Next, 200 cells from the high and low gate were sorted for qPCR analysis for a subset of tumor markers such as AMACR, CAMKK2, TMEFF2, REPS2 and ABCC4." (PMID 25514598, 2015). "We confirm a number of previously published molecular changes associated with high risk disease, including MYC amplification, and NKX3-1, RB1 and PTEN deletions, as well as over-expression of PCA3 and AMACR, and loss of MSMB in tumour tissue." (PMID 26501111, 2015). "Immunohistochemical findings showed that the tumor cells in all four cases were positive for AMACR, CK, CK7, CK19, EMA, HMWK, E-cadherin, and vimentin." (PMID 25476569, 2014). "The goal of our study was to investigate AMACR and iNOS expressions in PAs diagnosed in needle biopsies at our institute and correlate them with tumor grade." (PMID 24353588, 2013). "For the case group, AMACR expression in tumor tissues was determined by immunostaining and reclassified into two subgroups according to expression level: a negative group (score 0) versus a positive group (score 1+, 2+ or 3+)." (PMID 24383053, 2013). "All of the prostatic growth in recombinants containing cells isolated from tumor, non-tumor, or benign tissues was pathologically benign and only observed AMACR expression in one atrophic gland." (PMID 23383057, 2013). "P08-029pre, which came from a small tumor volume of 0.6 cc, showed marginal increase (2- to 3-fold above background) for these genes except for AMACR: AGR2 = 0.16, AMACR = 0.32, CRISP3 = 0.78, ERG = 0.28, HPN = 0.12, PCA3 = 0.19." (PMID 23029164, 2012). "AMACR overexpression in the tumour in direct comparison with adjacent normal tissue (‘tumour>normal’ ratio) was seen in 95% of cases." (PMID 18781151, 2008). "Various degree of expression of AMACR has also been reported in other types of neoplasms including HCC." (PMID 18577240, 2008). "However, our sample varied when comparing the staining of Vimentin (+) and AMACR (-) to the tumor samples found within the Al-Obaidy study." (PMID 40989704, 2025). "Most of the time, a double stain with p63 (a nuclear marker of the basal layers) and AMACR (alpha-methylacyl-CoA racemase, a cytoplasmatic marker of tumor cells) will be co-expressed in IDC-P and, therefore, together with morphology, guide the pathologist toward the right diagnosis." (PMID 38893122, 2024). "As a sensitive biomarker, AMACR has also been found in other neoplasms." (PMID 39858412, 2024). "In addition, correlations between AMACR expression and patient age, sex, and tumor size were evaluated." (PMID 39336516, 2024). "Moreover, the examination of gene expression and violin plots demonstrated a high expression of a group of AR signature genes, including KLK3, AR, TMPRSS2, NKX3.1, and AMACR across all clusters, indicating their tumor origin." (PMID 38732035, 2024). "AMACR was the top significantly up-regulated protein in the tumour tissue." (PMID 38052461, 2024). "Also, PDOs have consistent IHC‐positive staining of the well‐established tumor marker AMACR and show histological similarities to their original primary tumors." (PMID 36694344, 2023). "Interestingly, in 5/16 cases (3/5 ISUP grade 2, 2/5 ISUP grade 3) high [177Lu]Lu-PSMA-617 binding and in contrast no or very little [177Lu]Lu-NeoB binding was observed to cells outside the tumor region and AMACR positively stained areas (i.e. normal tissue)." (PMID 37719014, 2023).
tumor (continued). "In the majority of cases, these AMACR positive areas outside of the tumor region also showed relatively high [177Lu]Lu-PSMA-617 and [177Lu]Lu-NeoB binding and may represent premalignant high-grade PIN." (PMID 37719014, 2023). "Furthermore, the tumor volume of the mice that received the multiantigen vaccine was significantly lower compared to the mice receiving the AMACR (p < 0.0001), HPN (p = 0.019) or the PSMA (p = 0.002) single antigen vaccines." (PMID 35948756, 2022). "We are therefore working to add AMACR and p63 to our flow cytometry panel and are also planning to include global genomic and transcriptomic analyses of our PDCOs to evaluate for tumor-specific molecular alterations such as ERG, AR splice-variants, and NEPC markers." (PMID 34581895, 2021). "These analyses suggest that elevated AMACR expression and AMACR-mediated upregulation of fatty acid oxidation may promote aggressive tumor progression." (PMID 32674458, 2020). "These tumours express AMACR and CK7 on immunohistochemistry." (PMID 30123932, 2018). "Since NE-like tumor cells express AMACR, we investigated whether activation of OR51E2 also increased AMACR levels." (PMID 29892571, 2018). "The oncogenic role of AMACR in driving tumor growth was first unraveled in prostatic intraepithelial neoplasia and adenocarcinomas by cDNA microarray analysis, which, albeit with variable prognostic implication, was subsequently reported in several other carcinoma types." (PMID 25473890, 2014). "The basal cell marker P63 decorates only benign glands whereas AMACR is a marker for tumor cells." (PMID 21958464, 2011). "One prevailing hypothesis posits that AMACR functions as a gatekeeper of β-oxidation, and that its overexpression enables PCa cells to shift their metabolic reliance toward FA β-oxidation, thereby supporting tumor progression." (PMID 40647540, 2025). "Some studies have speculated that AMACR overexpression may lead to alterations in the balance of cellular oxidants through its role in fatty acid metabolism, which in turn may contribute to the pathogenesis of neoplasia." (PMID 33755595, 2021). "Regarding miR-26a, we previously showed that this miRNA is significantly downregulated in PCa tissue samples and could exert tumor-suppressive functions possibly by regulating genes that are upregulated in PCa, such as alpha-methylacyl-CoA racemase (AMACR) and enhancer of zeste homolog 2 (EZH2)." (PMID 32784833, 2020). "Given the involvement of AMACR in the metabolism of lipids, it was speculated that overexpression of this protein might lead to alterations in the balance of cellular oxidants, which in turn might contribute to the pathogenesis of neoplasms." (PMID 22782380, 2012). "Interestingly, AMACR also stained the endothelial cells in the vessels adjacent to the tumor." (PMID 21627811, 2011). "The tumor cells showed expression of PAX8, CA9, AMACR/P504S, Vimentin, CK7, CD10, FH, INI1(SMARCB1) and ELOC(TCEB1), and ELOC was mainly located in the nucleus." (PMID 41306531, 2025). "Immunohistochemically, the tumor demonstrated a characteristic profile with strong and diffuse positivity for CK7 and GATA3, focal positivity for CK20 and TFE3, and negativity for AMACR, CA IX, and CD10." (PMID 41367859, 2025). "In terms of immunohistochemical (IHC) staining, most tumor cells have been shown to stain positive for Vimentin, CD10, PAX8, and AMACR." (PMID 39234013, 2024). "In this report, nearly all tumor cells were positive for GATA-3, KRT7, EMA, E-Cadherin, Ksp-Cadherin, 34βE12, and AMACR in varying intensities, focally positive for CD10 and Vimentin, while negative for CD117, TFE3, RCC, and CAIX." (PMID 37143937, 2023). "In fact, during this study, some GC with uncertain malignant features according to morphological analyses, were shown to express tumor markers such as TERT, AMACR, or PSMA." (PMID 37444476, 2023). "Immunohistochemically (IHC), the tumor cells were CK7-intense and diffusely positive, and stained granular for AMACR." (PMID 36010254, 2022).
tumor (continued). "ERG+ tumor cells were characterized by expression of ERG and tumor markers PCA3, AMACR, and TRPM8;35–37ERG− tumor cells were marked by the expression of tumor markers PCA3 and TRPM835–37." (PMID 35013146, 2022). "The tumours have a typical profile on immunohistochemistry, including strong CK7 and alpha-methylacyl-CoA racemase (AMACR) expression and at most focal CA-IX expression." (PMID 30123932, 2018). "The positivity of the tumor for CK7, β-catenin in a membranous/cytoplasmic staining pattern, CDX2, and AMACR, and negativity for CK20, p63, PSA, and PSAP, favored a vesical rather than a colorectal or prostatic origin." (PMID 27006847, 2016). "Some tumor markers such as AMACR, TMEFF2 and ABCC4 were also expressed in mesenchymal cells or lymphocytes at levels comparable to AMACR low cells." (PMID 25514598, 2015). "In line with our previous observations, the tumor markers AMACR, CAMKK2, TMEFF2, REPS2 and ABCC4 were significantly expressed in AMACR high cells as compared to AMACR low cells." (PMID 25514598, 2015). "The tumor in our case was diagnosed as a type 2 PRCC due to its morphological features, lack of expression for CK7, and positivity for EMA, Vimentin, and AMACR." (PMID 26301110, 2015). "Immunohistochemical assay demonstrated that the tumor cells of MTSC and sPRCC were positive for AMACR, CK, CK7, CK19, EMA, HMWK, E-cadherin, vimentin and Ki - 67 index was <5%." (PMID 25476569, 2014). "Also, tumor glands showed positive staining for racemase (alpha-methylacyl-CoA racemase, also known as AMACR or P504S; encoded by the AMACR gene), negative (or weakly positive) staining for CK5 (a prostate basal epithelial marker), and negative staining for p63 (another basal cell marker)." (PMID 23451107, 2013). "Furthermore, AMACR expression may not be limited to tumours linked to dietary factors and may be involved in carcinogenesis via a degradation pathway of branched-chain fatty acids, or an epiphenomenon." (PMID 22782380, 2012). "The tumor was positive for AMACR, negative for GATA3, and rarely/focally positive or completely negative for CK7 and CAIX." (PMID 39703302, 2024). "Of the top 20 differentially expressed proteins identified in tumour samples, four (MDH2, FASN, EPCAM, and HSD17B10) are targetable by FDA-approved drugs, whereas two (AMACR and GLYATL1) are potentially targetable and are of potential interest for future research." (PMID 38052461, 2024). "We detected varying expression levels of the immunohistochemical markers CK20, PAX-8, and AMACR in the tumor cells of our patient, but not of CD117, CK7, CD10, and CA IX." (PMID 37098579, 2023). "Immunohistochemically, tumours expressed CK7, AMACR and PAX8." (PMID 37649003, 2023). "For instance, a rectal biopsy with submucosal location of a poorly differentiated tumour was diagnosed as metastatic prostatic adenocarcinoma as the tumour cells were negative for SATB2 but positive for PSA and Alpha Methyacyl CoA racemase (AMACR)." (PMID 36200017, 2022). "Tumor samples contained AMACR+ tumor cells and lacked a p63+ basal cell layer, whilst non-tumorigenic prostate glands did not express AMACR and retained a defined p63+ basal cell layer." (PMID 33799802, 2021). "Second, both NE tumor cells and non-NE tumor cells express the β-oxidation enzyme α-methylacyl-CoA-racemase (AMACR), a recently identified marker that is strongly associated with PCa risk." (PMID 25785244, 2015). "In contrast, luminal benign epithelial cells show weak or absent staining for AMACR, whereas epithelial tumor cells show in most cases strong staining for AMACR instead." (PMID 25514598, 2015). "To elucidate whether AMACR was not only a passenger accompanied by +5p, we quantified AMACR mRNA in LCM-isolated tumor cells from fresh samples and found a significantly higher expression level in samples of higher risk categories (Figure-1D, p=0.01)." (PMID 25473890, 2014).
tumor (continued). "However, both markers also showed remarkable differences, particularly, when the tumour/normal ratio of GOLPH2 and AMACR was considered." (PMID 18781151, 2008). "No KIT, CD10, CA9, GATA3 or alpha-methylacyl-CoA racemase was detected in the tumor cells." (PMID 39980061, 2025). "Immunohistochemical analysis using the recommended minimum antibody panel (CAIX, TFE3, PAX8, HMB-45 and Melan-A, Cathepsin K, AMACR, CK-7, EMA) could be advised routinely for every case of RCC, regardless of the patient′s age and the microscopic features of the tumor." (PMID 35886994, 2022). "Our study shows that the low expression of AMACR is related with the absence of tumor capsule, indistinct tumor boundary as well as presence of portal vein tumor thrombosis (PVTT) and intraoperative ascites, which fits with the earlier recurrence/metastasis of AMACR lower expression group." (PMID 24839399, 2014). "AMACR was not expressed in the non-neoplastic gastric mucosa surrounding each tumour." (PMID 22782380, 2012). "We observed an overexpression of both AMACR and AR mRNA in not only cancerous, but also in histologically benign tissue from prostates with clinically significant carcinomas when they were compared to prostates without tumor or harboring only incidental lesions." (PMID 26928323, 2016). "The tumor was histologically composed of oncocytic cells that expressed KRT7, vimentin, SDHA, SDHB and fumarate hydratase, but not KIT, GATA3 and alpha-methylacyl-CoA racemase." (PMID 39980061, 2025). "Immunohistochemically, the tumor cells were positive for GATA-3, CK7, and EMA (apical membranous) while negative for AMACR and CA IX." (PMID 40989704, 2025). "The tumor cells were positive for PAX8, weakly and focally positive for CK20, CKAE1/AE3, CD10, and AMACR, and negative for CK7, CD117, MelanA, HMB45, TFE3, Actin, and ALK." (PMID 38892169, 2024). "Immunohistochemically, the tumor cells were positive for cytokeratin 7 (CK7) and focally positive for α-methylacyl-coenzyme A racemase (AMACR, also called p504s) but negative for thyroid transcription factor-1." (PMID 35449090, 2022). "On immunohistochemistry (IHC), the tumor cells were strongly and diffusely positive for CK7, while being negative for CD117, vimentin and Alpha-methylacyl-CoA racemase (AMACR)." (PMID 34514579, 2022). "On IHC, the tumor cells were strongly and diffusely positive for CK7, while being negative for CD117, CD10, AMACR, Synaptophysin and Chromogranin." (PMID 34514579, 2022). "Although the lymph node metastasis and the negativity of AMACR are not typical findings of MTSCC, we initially diagnosed this tumor as MTSCC based on its morphological characteristics with mucin deposition." (PMID 35718773, 2022). "Immunohistochemistry showed the tumour cells to strongly express PAX8, Vimentin, CAM5.2, AMACR and EMA, focal E-cadherin expression with no tumour expression of CD10, RCCAg, CK7, or CD117." (PMID 27005674, 2016). "Alpha-methylacyl-coenzyme A-racemase (AMACR/P504S), calretinin, CD10 and thyroid transcription factor-1 (TTF-1) did not stain any of the three components of the tumor." (PMID 19523243, 2009). "The tumours are positive for AMACR, CK7, Vimentin, and CD10 and need to be differentiated from papillary neoplasm with reverse polarity which are GATA3 positive, vimentin negative, and AMACR positive." (PMID 38265103, 2024). "Although the tumor cells were negative for immunohistochemistry (IHC) of alpha-methylacyl-CoA racemase (AMACR) and lymph node metastasis was presented (these are atypical findings for MTSCC), we initially diagnosed the tumor as MTSCC based on its morphological characteristics with mucin deposition." (PMID 35718773, 2022).